TWF1 (twinfilin actin binding protein 1)
Diseases named in the same sentence as TWF1 in open-access papers (continued):
Sharing a sentence is not in itself a finding about the gene and the disease.
tumor (continued). "Considering the role of TWF1 in the regulation of actin cytoskeleton structure, and the known role of actin cytoskeleton in cell migratory processes, we hypothesized that altered TWF1 expression level or its genetic alteration may impact the tumor infiltrating immune cell response." (PMID 34113576, 2021). "Thus, we next wanted to explore the TWF1 genetic alterations in human tumor samples." (PMID 34113576, 2021). "Thus, we next compared the phosphorylation of TWF1 between normal and primary tumor tissues." (PMID 34113576, 2021). "Thus, we applied the TIMER, CIBERSORT, CIBERSORT-ABS, TIDE, XCELL, MCPCOUNTER, QUANTISEQ and EPIC algorithms to explore the correlation between the infiltration level of different immune and endothelial cells and TWF1 expression in multiple tumor types of TCGA." (PMID 34113576, 2021). "miR-1 acts as a tumor suppressor, promoting the inhibition of tumor growth and acting with multiple target genes, such as CDK4, TMSB4X, WASF2, TWF1, CNN3, and CORO1C which are genes involved in cell cycle and metastasis." (PMID 38813102, 2024). "Twinfilin 1 (TWF1) as an inhibitor of the actin polymerization is involved in regulation of cell migration, drug sensitivity, and tumor progression." (PMID 37580768, 2023). "In the case of CDC42, the TWF1 and SELT genes were identified as co-expressed in all three groups: healthy tissue, adjacent healthy tissue, and tumor tissue." (PMID 37365287, 2023). "hsa-miR-486-5p inhibits tumor growth and improves chemotherapy sensitivity by targeting PIK3R1 (phosphoinositide-3-kinase regulatory subunit 1) and TWF1 (twinfilin actin binding protein 1), respectively." (PMID 35118066, 2021). "MiR-30c was previously reported to play a suppression role in tumour cell proliferation, metastasis and drug resistance by targeting BCL9, TWF1, vimentin and KRAS." (PMID 24595016, 2014). "Normal lung, breast, ovary, liver, testis, and thyroid tissues showed negative or moderate staining for TWF1 IHC, whereas tumor tissues showed moderate or strong staining." (PMID 37713832, 2023). "Normal lung, breast, ovary, liver, testis, and thyroid tissues had negative or medium TWF1 IHC staining, while tumor tissues had medium or strong staining." (PMID 34113576, 2021). "Other up regulated cellular proteins which were identified included the cytoskeletal-related actin binding protein Twinfilin-1 (TWF1) (Rsc 5.1), and the tumor suppression-related proteins Apolipoprotein A-1 (APOA1) (Rsc 5.1) and Eukaryotic release factor 1 (ETF1) (Rsc 2.3)." (PMID 28406185, 2017).
cancer (10 papers, 2012 to 2025). A tumor composed of atypical neoplastic, often pleomorphic cells that invade other tissues. "TWF1 gene encodes an actin monomer-binding protein, which is essential for cytoskeletal remodeling, myogenic differentiation and cancer progression." (PMID 39844043, 2025). "The link between TWF1 and endothelial cell, neutrophil or cancer-associated fibroblast infiltration." (PMID 34113576, 2021). "As a consequence, TWF1 is involved in the regulation of diverse morphological and motile processes, and has been implicated in cell motility, sensitivity to drugs and cancer progression." (PMID 34113576, 2021). "The emerging literature highlights TWF1’s role in drug sensitivity and cancer progression, indicating its potential as a therapeutic target." (PMID 40362400, 2025). "Our pan-cancer analysis provides a comprehensive overview of the oncogenic roles of TWF1 in multiple human cancers." (PMID 34113576, 2021). "This comprehensive analysis reveals potential molecular mechanism of TWF1 in the pathogenesis and clinical prognosis of multiple human cancers." (PMID 34113576, 2021). "Growing number of studies have focused on the analysis of the function of TWF1 in diseases, including cancer." (PMID 34113576, 2021). "This comprehensive pan-cancer analysis provides a very thorough overview of the oncogenic roles of TWF1 in multiple human cancers." (PMID 34113576, 2021). "The TMSB4X, CNN3, TWF1, CORO1C and WASF2 genes encode cytoskeletal proteins related to actin filament dynamic regulation, and they are involved in cancer metastasis." (PMID 28159933, 2017). "We evaluated the transfection efficiency of the miRNAs in cancer cell lines based on the downregulation of mRNA expression levels of protein tyrosine kinase 9 (PTK9, alias as twinfilin: TWF1) after miR-1 transfection." (PMID 22068816, 2012). "Besides, The responsiveness of these cell lines to anti-cancer drugs such as doxorubicin and paclitaxel is augmented by siRNA inhibition of TWF1 expression." (PMID 34249670, 2021). "Interestingly, we discovered a negative correlation of TWF1 expression and the estimated infiltration value of cancer-associated fibroblasts for the STAD and TGCT." (PMID 34113576, 2021). "Thus, here we set out to perform a pan-cancer analysis of TWF1." (PMID 34113576, 2021).
infection (5 papers, 2011 to 2023). The state of being infected such as from the introduction of a foreign agent such as serum, vaccine, antigenic substance or organism. "Only 3 (ABCF3, CNEP1R1, TWF1) out of 11 genes shared between moDC and cDC2 were up-regulated in response to infection." (PMID 33365028, 2020).
TWF1 also shares sentences with these, for which no sentence is quoted: glioblastoma (2 papers); amyloid (1); cervical cancer (1); cervical squamous cell carcinoma (1); cholangiocarcinoma (1); cholangiomas (1); chronic lymphocytic leukemia (1); colitis (1); colon adenocarcinoma (1); coronary artery disease (1); endocervical adenocarcinoma (1); endometrial carcinoma (1); Esophageal carcinoma (1); head and neck squamous cell carcinoma (1); heart failure (1); hepatocellular carcinoma (1); ischemia (1); Kidney Chromophobe (1); liver fibrosis (1); Lung squamous cell carcinoma (1); lymphoma (1); non-small cell lung carcinoma (1); ocular coloboma (1); ovarian carcinoma (1); pancreatic adenocarcinoma (1); prostate carcinoma (1); rectum adenocarcinoma (1); sarcopenia (1); Stomach adenocarcinoma (1); ZIKV infection (1).
A further 1 disease shares a sentence with TWF1 in 1 paper.